SECISBP2L (SECIS binding protein 2 like)
Description:
Binds SECIS (Sec insertion sequence) elements present on selenocysteine (Sec) protein mRNAs, but does not promote Sec incorporation into selenoproteins in vitro.
Synonyms: KIAA0256; SBP2L; SLAN
Tractability: PROTAC: ubiquitination databases record sites on it.
Gene: Protein-coding gene on chromosome 15 (48,988,476 to 49,046,477, reverse strand). Ensembl gene ENSG00000138593.
Subcellular location (Human Protein Atlas): Nucleoplasm
Gene Ontology:
Molecular function: protein binding; RNA binding; mRNA 3'-UTR binding; ribonucleoprotein complex binding; selenocysteine insertion sequence binding
Biological process: selenocysteine incorporation
Cellular component: mitochondrion; ribonucleoprotein complex
Genetic constraint (gnomAD): Loss-of-function variants: 40 observed, 107.75 expected, observed/expected ratio (o/e) 0.37, 90% interval 0.29 to 0.48. The upper end of that interval is the gene's LOEUF score, 0.48, which puts it in group 2 of 6, group 1 being the genes least tolerant of losing a copy. Missense variants: 1,101 observed, 1,307.3 expected, observed/expected ratio (o/e) 0.84, 90% interval 0.8 to 0.88. Synonymous variants: 442 observed, 441.5 expected, observed/expected ratio (o/e) 1, 90% interval 0.93 to 1.08.
Homologues: Orthologues: chimpanzee SECISBP2L (99% identical), macaque SECISBP2L (99% identical), dog SECISBP2L (95% identical), rabbit SECISBP2L (94% identical), pig SECISBP2L (94% identical), rat Secisbp2l (87% identical), mouse Secisbp2l (87% identical), guinea pig SECISBP2L (85% identical), tropical clawed frog secisbp2l (70% identical), Drosophila melanogaster Sbp2 (8% identical). Paralogues in human: SECISBP2 (22% identical).
Diseases named in the same sentence as SECISBP2L in open-access papers:
SECISBP2L is named in the same sentence as 17 diseases in open-access papers, as found by Europe PMC text mining. Sharing a sentence is not in itself a finding about the gene and the disease. The quoted sentences say what the papers report.
lung carcinoma (6 papers, 2020 to 2024). "Predicted expression of seven genes was significantly (p < 5.0 × 10−4) associated with lung cancer risk: SECISBP2L, HLA-L, DISP2, MAPT, KANSL1-AS1, LRRC37A4P, and PLEKHM1." (PMID 31911640, 2020). "The study identified RNASET2, SECISBP2L,NRG1, CHRNA2, OFBC1 and RTEL1 as candidate genes associatedwith lung cancer." (PMID 33959694, 2020). "This gene was among several susceptibility regions identified in the most recent lung cancer GWAS16, and now we more conclusively establish impaired pulmonary function as the mechanism mediating SECISBP2L effects on risk of lung cancer overall, particularly adenocarcinoma." (PMID 31911640, 2020). "Previous studies have shown downregulation of SECISBP2L and HLA-DRB5 in lung cancer, with HLA-DRB5 expression inversely correlated with LUAD risk." (PMID 39092217, 2024).
anxiety disorder (1 paper, 2021). A category of psychiatric disorders which are characterized by anxious feelings or fear often accompanied by physical symptoms associated with anxiety. "Several DEGs shared by the male Tg and NTg have previously been linked to early-life stress, anxiety disorders and ADHD (Erbin), sex-specific gene expression in ASD and dopamine changes (Erbb2ip, Neurod6), and to TH-dependent growth and embryonic differentiation processes (Secisbp2l)." (PMID 34100083, 2021).
colon cancer (1 paper, 2022). "However, a recent colon cancer study stated that SECISBP2L showed high expression in the LN (+) group rather than the LN (−) group, and the expression level was significantly correlated with the survival rate." (PMID 35055428, 2022).
Headache (1 paper, 2022). Cephalgia, or pain sensed in various parts of the head, not confined to the area of distribution of any nerve. "Of the genes at these loci, six (FAF1, TMX2-CTNND1, AARSD1, PLCD3, ZNF652, and C20orf203; headache-TSH) and six (HMGB1P45, RPL30P1, ZNF462, TMX2-CTNND1, ITPK1, SECISBP2L; headache-fT4) were significant in our gene-based analysis (pFisher’s combined p-value < 2.09 × 10−6)." (PMID 36672757, 2022).
lung adenocarcinoma (1 paper, 2024). A carcinoma that arises from the lung and is characterized by the presence of malignant glandular epithelial cells. "There were 6 genes with a causal relationship to lung adenocarcinoma, including FUBP1, CTD-2012J19.3, CTD-2012J19.1, DCBLD1, NRG1 and SECISBP2L." (PMID 38834983, 2024).
lymph node metastasis (1 paper, 2022). "The mutated genes associated with lymph node metastasis were SECISBP2L (p = 2.20e-16, r = 1.000) and KDM5C (p = 0.00038, r = 0.690); both of these showed a very strong association." (PMID 35055428, 2022). "In this study, we identified SECISBP2L (p = 2.20e-16, r = 1.000) and KDM5C (p = 0.00038, r = 0.690) as genes associated with lymph node metastasis." (PMID 35055428, 2022).
melanoma (1 paper, 2021). A malignant, usually aggressive tumor composed of atypical, neoplastic melanocytes. "In the case of melanoma (MEL), high novelty targets are SPPL2A, CHL1, AP4E1, SECISBP2L, and COPS2." (PMID 34570764, 2021).
squamous cell carcinoma (1 paper, 2020). A carcinoma arising from squamous epithelial cells. "Differences by histology were observed for SECISBP2L, which was associated with adenocarcinoma (OR = 0.54, p = 3.1 × 10−14), but not squamous cell carcinoma (OR = 1.05, p = 0.44)." (PMID 31911640, 2020).
cancer (3 papers, 2020 to 2024). A tumor composed of atypical neoplastic, often pleomorphic cells that invade other tissues. "The Pearson’s correlation test revealed that the presence of mutations in SECISBP2L was closely related to the spread of cancer cells to the lymph nodes and also showed a significant association with mortality (p = 0.03, r = 0.463)." (PMID 35055428, 2022). "Interestingly, Type II Alveolar Epithelial Cells specifically enrich for the SECISBP2L gene in adjacent non-cancerous tissues, while HLA-DRB5 gene is enriched in cancer tissues." (PMID 39092217, 2024).
SECISBP2L also shares sentences with these, for which no sentence is quoted: tumor (3 papers); glioblastoma (2); adenocarcinoma (1); glioma (1); HIV-1 infection (1); infection (1); latent infection (1); prostate carcinoma (1).